L1CAM (L1 cell adhesion molecule)
Diseases named in the same sentence as L1CAM in open-access papers (continued):
Sharing a sentence is not in itself a finding about the gene and the disease.
endometrial cancer (continued). "When compared with normal endometrial tissue L1CAM mRNA levels were significantly higher in endometrial cancers (p< 0.0001)." (PMID 27233077, 2016). "More specifically, the prognostic value of L1CAM for patients with ovarian cancer, endometrial cancer, neuroendocrine tumours, colorectal cancer, and hepatocellular cancer were eminently remarkable." (PMID 27833079, 2016). "By the best of our knowledge, this is the first study evaluating the L1CAM status in endometrial cancer on the transcriptome level using qRT-PCR on fresh frozen tissue samples." (PMID 27233077, 2016). "This study aimed at the validation of L1CAM as marker of poor disease-free and overall survival in early stage endometrial cancer." (PMID 27488577, 2016). "Subgroup analyses based on cancer types revealed significant reverse associations between L1CAM expression and DFS in neuroblastoma, ovarian cancer, neuroendocrine tumours, gallbladder cancer, hepatocellular cancer and endometrial cancer." (PMID 27833079, 2016). "More recently, these findings were confirmed in an analysis of L1CAM expression in endometrial cancers from two randomised controlled trials (PORTEC-1 and -2) and in a multicentre retrospective study conducted by the ENITEC consortium." (PMID 27488577, 2016). "The issue of the positive rate of L1CAM in endometrial cancer is of great importance to allow adequate cohort estimations when L1CAM-based clinical studies are planned in future." (PMID 27233077, 2016). "The overexpression of L1CAM in ovarian and endometrial cancer has a critical value in patient outcome prediction." (PMID 27833079, 2016). "In this study, the mixed endometrial carcinomas showed L1CAM-expression in the serous component, whereas the endometrioid component was L1CAM-negative." (PMID 26891628, 2016). "Expression of L1CAM has been found to correlate with poor prognosis and metastasis in ovarian and endometrial carcinomas." (PMID 26879132, 2016). "For the best of our knowledge this pilot study for the first time analyses L1CAM expression by RT-PCR in a training set of 82 endometrial carcinoma samples." (PMID 27233077, 2016). "A large prospective study is required to determine the clinical implications of L1CAM in endometrial carcinomas." (PMID 26891628, 2016). "L1CAM expression has been found in gynecological carcinomas such as ovarian and endometrial cancers but was also reported to be present in a low percentage of breast carcinomas." (PMID 25510351, 2014). "Given the recent findings about the molecular similarities between high-grade serous ovarian, endometrial cancers and certain forms of breast cancer we re-investigated L1CAM in breast cancer in more detail." (PMID 25510351, 2014). "In endometrial carcinoma we have previously identified the transcription factor Slug as a positive regulator for L1CAM." (PMID 25510351, 2014). "Our findings suggest that Slug plays a major role in the regulation of L1CAM in endometrial cancer and pancreatic cancer." (PMID 20799950, 2010). "The treatment of endometrial carcinoma cells with the EMT-inducer TGF-β1 augmented L1CAM expression and downregulation of E-Cadherin and this process was blocked by knockdown of Slug." (PMID 20799950, 2010). "Next, we investigated the site of transcriptional initiation of the human L1CAM gene in endometrial carcinoma cell lines." (PMID 20799950, 2010). "Therapeutic strategies targeting the L1CAM-NF-κB pathway may represent a promising treatment option for improving prognosis in L1CAM-positive human endometrial cancer." (PMID 41595121, 2026). "Interestingly, in endometrial cancer cell lines, the presence of FBXW7 mutations affects the protein levels of L1CAM." (PMID 40870967, 2025). "A study of these structures in endometrial cancer revealed that L1CAM is expressed inside the lymphoid structures from follicular dendritic cells independently from its tumor expression, and that this L1CAM-expressing lymphoid structure is an independent prognostic factor." (PMID 40870967, 2025).
endometrial cancer (continued). "The prognostic importance of L1CAM in endometrial cancer suggests that it could be used as a therapeutic target." (PMID 40870967, 2025). "L1CAM seems to predict the response of endometrial cancer to chemotherapy." (PMID 40870967, 2025). "Whether targeting L1CAM is a therapeutic option also remains unknown, but it is worth investigating in endometrial cancer." (PMID 40870967, 2025). "L1CAM (L1 adhesion molecule) is a type I membrane glycoprotein of the immunoglobulin superfamily (IgSF), which was found to be expressed in a plethora of human tumors, including endometrial cancers." (PMID 40422510, 2025). "At almost the same time, a similar study compared the L1CAM in 241 endometrial biopsies to that of paired hysterectomy specimens of 75 patients; the serum levels of L1CAM were also measured in 40 patients with endometrial carcinoma." (PMID 40870967, 2025). "Therefore, it demonstrated that the L1CAM can be a predictor of poor outcome in endometrial carcinoma." (PMID 40927288, 2025). "Regarding the diagnostic value of L1CAM, it has been proposed that L1CAM expression, together with IMP3 (insulin-like growth factor-II mRNA-binding protein 3) expression, can accurately distinguish low-grade from high-grade endometrial carcinomas." (PMID 40870967, 2025). "In TCGA analysis, high L1CAM was significantly correlated with advanced stage, grade, serous histology, positive cytology, positive pelvic and para-aortic lymph nodes, and shorter OS in univariate analysis of endometrial carcinomas." (PMID 40422510, 2025). "Furthermore, various studies have highlighted the role of L1CAM in endometrial cancer, fostering significant expectations for its potential clinical applications." (PMID 39734232, 2024). "DTCs were previously reported not to be associated with established risk factors, L1CAM immunoreactivity, and outcome in endometrial carcinoma (EC)." (PMID 39124757, 2024). "In this comprehensive analysis of 648 high-risk EC, we evaluated the prognostic value of ER, PR, L1CAM and CTNNB1 mutations and established clinicopathologic and molecular risk factors in one of the largest cohorts of molecularly classified high-risk endometrial cancers worldwide." (PMID 36690721, 2023). "Evidence suggests that L1CAM expression is a marker of worse prognosis in endometrial cancer." (PMID 33672863, 2021). "In conclusion, L1CAM alone or its integration with established clinicopathological features in endometrial cancer does not improve risk stratification with potential therapeutic implications in the lymph node surgery." (PMID 34659530, 2021). "In a different study that analysed biopsies from 1134 endometrial cancer patients, L1CAM high expression predicted poor disease-specific survival – defined as time from surgery to death – both in the entire cohort and among low-risk patients, who normally receive no or limited adjuvant treatment." (PMID 32429448, 2020). "In addition, the authors evaluated the serum level of soluble L1CAM (sL1CAM) in preoperative samples from a subgroup of 372 patients with endometrial cancer." (PMID 32429448, 2020). "In addition, the Human Protein Atlas database also indicated that L1CAM was a prognostic marker in endometrial cancer (unfavorable), lung cancer (unfavorable), renal cancer (unfavorable), head and neck cancer (unfavorable), and other solid cancers." (PMID 32509846, 2020).
endometrial cancer (continued). "According to the findings, in low-risk endometrial carcinoma, it has been suggested to limit the term “low-risk endometrial carcinoma” to L1CAM-negative tumors." (PMID 32927671, 2020). "Again, this could seem surprising in view of recent data suggesting L1CAM to be the most reliable prognostic factor in endometrial cancer." (PMID 27832351, 2017). "Due to its expression being specific to the Mullerian tract-derived cancers like ovarian and endometrial cancer, L1CAM has been suggested as a possible marker differentiating those carcinomas from cases of metastatic cancer of unknown primary site in women." (PMID 27832351, 2017). "Expression of L1CAM has been reported as an independent prognostic factor for disease-free survival in ovarian cancer, neuroendocrine tumors, gallbladder cancer, hepatocellular cancer and endometrial cancer." (PMID 29152102, 2017). "In the L1CAM-positive endometrial cancers, like in colon and ovarian cancers, the L1CAM may often be found at the leading edge of the cancer—the area, which also tends to be E-cadherin and ER/PR negative." (PMID 27832351, 2017). "In endometrial cancer an inverse correlation between miR-34a and L1CAM expression was found." (PMID 27174921, 2016). "Although, in the present approach L1CAM expression was revealed to be significantly higher in cancer samples as compared with healthy endometrium, the large majority of endometrial cancers proved either to lack L1CAM expression at all or to exhibit only very weak L1CAM expression." (PMID 27233077, 2016). "Therefore a systemic treatment with a humanized anti-L1CAM antibody, which is currently under investigation, should be considered as an alternative treatment option in endometrial cancer." (PMID 27233077, 2016). "Importantly, in endometrial carcinoma cell lines L1CAM has also been shown to be inhibited by DNA methylation of its promoter and by various miRNAs whereby the most reliable data exist for miR-34a." (PMID 27233077, 2016). "Moreover, to substantiate the in vitro findings of the regulation of L1CAM expression we analysed also for the first time L1CAM promoter methylation, miR-34a expression and miR-34a promotor methylation in endometrial carcinoma tissue samples." (PMID 27233077, 2016). "In serous ovarian and endometrial carcinomas, L1CAM-expression is frequently present." (PMID 26891628, 2016). "When the four principal molecular subtypes of endometrial carcinomas started to appear as important prognosticators of this disease, the question of whether L1CAM is just a consequence of one of these subtypes—and therefore not an independent prognostic factor—began to be raised." (PMID 40870967, 2025). "As both L1CAM expression and MELF pattern are related to epithelial to mesenchymal transition and, likely, to metastatic spread, we aimed to assess (i) the relationship between these two factors in endometrial carcinoma and (ii) their association with lymph node metastasis." (PMID 35892892, 2022). "Owing to the fact that marker testing on curettage samples has proven equally reliable as on hysterectomy specimens 25, 26, it might be proposed to use L1CAM in the preoperative risk stratification to predict lymph node metastasis in endometrial cancer." (PMID 34659530, 2021). "Thus, L1CAM is a novel biomarker for the prognosis of serous ovarian and endometrial cancers." (PMID 25510351, 2014).
endometrial cancer (continued). "Slightly later, the Postoperative Radiation Therapy in Endometrial Carcinoma (PORTEC)-1 and -2 trials cohort was used to test L1CAM’s prognostic role." (PMID 40870967, 2025). "Furthermore, it has been reported that L1CAM enhances the invasion and metastasis of cancer cells in several types of cancer, and its elevated expression seems to correlate with shorter survival in patients with cancer, including endometrial cancer, ovarian cancer, and NSCLC." (PMID 39201435, 2024). "In our study, we aimed to assess the relationship between L1CAM expression and the MELF pattern of invasion in endometrial carcinoma, as they are both related to epithelial to mesenchymal transition and aggressiveness." (PMID 35892892, 2022). "We aimed to assess the relationship between L1CAM expression, MELF glands, and lymph node involvement in endometrial carcinoma, as all these factors are related to epithelial-to-mesenchymal transition." (PMID 35892892, 2022). "Five most significant genes were selected, including L1CAM (L1 cell adhesion molecule), PRKCI, ESR1, CDKN2A and VIM, to construct a prognostic model for endometrial cancer." (PMID 34659539, 2021). "In this study, L1CAM, PRKCI and CDKN2A were the most relevant genes affecting survival in endometrial cancer, with high amounts reflecting poor prognosis." (PMID 34659539, 2021). "In a recent multicenter study, L1CAM has been called “the best ever published prognostic factor in FIGO stage I, type I endometrial cancers”." (PMID 27832351, 2017). "In fact, whole tissue RT-PCR may underestimate L1CAM positivity because it may be unable to adequately assess unevenly distributed L1CAM expressing small cell clusters, which have been frequently shown with IHC in endometrial cancer and were found to be of clinical relevance." (PMID 27233077, 2016). "Previous studies have reported that among endometrial cancer cell lines, HEC155 and ECC1 have the highest levels of L1CAM, a marker for endometrial cancer recurrence." (PMID 27121063, 2016). "What’s more, LAY reported that interleukin 11 regulated endometrial cancer cell adhesion and migration via STAT3102, and L1 cell adhesion molecule is a strong predictor for distant recurrence and overall survival in early stage endometrial cancer." (PMID 26373443, 2015). "We observed that L1CAM positive endometrial carcinoma (EC) cell lines HEC1B and SPAC1L lost L1CAM protein and mRNA by treatment with demethylating agents or knock-down of the DNA-methyltransferase-1 (DNMT1)." (PMID 24497324, 2014). "No independent prognostic significance was noted for L1CAM (tissue microarrays, clone 14.10, dilution 1:100, 10% cutoff) in another study of 335 endometrial cancer patients." (PMID 40870967, 2025). "On the contrary, another study comparing the serum levels of L1CAM between endometrial cancer patients and non-cancerous patients showed significantly higher levels for the first group." (PMID 40870967, 2025). "L1CAM overexpression (≥10%) and the microcystic, elongated, and fragmented (MELF) pattern of invasion have previously been assessed as prognostic factors in endometrial carcinoma." (PMID 35892892, 2022). "A multicentric study named ENITEC, which involved 10 different European centers, assessed L1CAM expression in 1199 cases that included early and late-stage endometriod endometrial cancers (EECs) as well as non-endometriod endometrial cancers (NEECs)." (PMID 32429448, 2020). "Moreover, L1CAM expression was accompanied by the upregulation of Musashi-1 and CD133, both considered to be CSC markers in endometrial cancer." (PMID 32429448, 2020).
endometrial cancer (continued). "Another study showed that L1CAM is highly expressed in recurrent respect to non-recurrent endometrial cancer and correlates with lower disease-free survival." (PMID 32429448, 2020). "Very recently, L1CAM expression was also found to correlate with distant recurrence in early-stage endometrial cancer patients with negative peritoneal cytology, a subgroup that normally has a relatively good prognosis." (PMID 32429448, 2020). "Secondly, many other immunohistochemical markers such as the serum Ca125, the L1 cell adhesion molecule, PTEN have been proved to be related to the prognosis of endometrial cancer in other studies, and the molecular classification proposed by TCGA has gained prominence in recent years." (PMID 33585205, 2020). "Endometrial cancers rated negative for both inhibitory mechanisms presented with higher L1CAM values as compared to tumors which showed significant inhibitory activity in both systems (p = 0.011)." (PMID 27233077, 2016). "Another marker, L1CAM, has been found to be a negative prognostic marker for Type I, stage I endometrial cancer and predicts need for adjuvant therapy." (PMID 27121063, 2016). "In the large majority of the endometrial cancer samples, L1CAM expression measured by RT-PCR was either absent or very weak." (PMID 27233077, 2016). "The evaluation of L1CAM expression in MELF glands may be integrated in the prognostic stratification of endometrial carcinoma, regardless of the overall expression in the whole tumor." (PMID 35892892, 2022). "Moreover, although not statistically significant, the expression of L1CAM, a poor prognostic factor in endometrial cancer, was twice as common in normal-weight patients as in overweight/obese patients." (PMID 33232359, 2020). "We therefore could not assess the correlation between the L1CAM serum level and endometrial cancer histopathological type, due to a relatively small group of non-endometrioid cancers." (PMID 27832351, 2017). "However, so far there are no clinical data available on chemosensitivity of L1CAM positive endometrial cancers." (PMID 27233077, 2016). "Similarly, in a cohort of 94 patients with endometrial cancer, L1CAM expression was of prognostic value only in the non-specific molecular profile subgroup, and in these patients, its expression was associated with early relapse after platinum-based chemotherapy." (PMID 40870967, 2025). "Thus, L1CAM-negative endometrial cancers tend to be E-cadherin and ER/PR positive." (PMID 27832351, 2017).